ANKRD40CL (ANKRD40 C-terminal like)
Synonyms: C17orf73; LINC00483; FLJ20694
Tractability: No criterion of Open Targets' tractability assessment is met for any kind of drug.
Gene: Protein-coding gene on chromosome 17 (50,760,971 to 50,767,570, reverse strand). Ensembl gene ENSG00000167117.
Homologues: Orthologues: macaque ANKRD40CL (92% identical), pig ANKRD40CL (80% identical), mouse Ankrd40cl (69% identical), rat Ankrd40cl (68% identical), tropical clawed frog ankrd40 (56% identical), zebrafish ankrd40 (56% identical). Paralogues in human: ANKRD40 (61% identical).
Diseases named in the same sentence as ANKRD40CL in open-access papers:
ANKRD40CL is named in the same sentence as 10 diseases in open-access papers, as found by Europe PMC text mining. Sharing a sentence is not in itself a finding about the gene and the disease.
ANKRD40CL shares sentences with these, for which no sentence is quoted: tumor (7 papers); gastric cancer (5); cancer (4); colorectal cancer (2); endometrial cancer (1); hepatocellular carcinoma (1); lung adenocarcinoma (1); nasopharyngeal carcinoma (1); non-small cell lung carcinoma (1); stomach adenocarcinoma (1).